TP53TG3 (TP53 target 3)
Synonyms: TP53TG3A; P53TG3
Tractability: No criterion of Open Targets' tractability assessment is met for any kind of drug.
Gene: Protein-coding gene on chromosome 16 (32,673,528 to 32,676,165, reverse strand). Ensembl gene ENSG00000183632.
Subcellular location: Cytoplasm; Nucleus
Subcellular location (Human Protein Atlas): Centriolar satellite
Gene Ontology:
Cellular component: cytoplasm; nucleus
Homologues: Paralogues in human: TP53TG3B (100% identical), TP53TG3C (100% identical), TP53TG3D (100% identical), TP53TG3E (100% identical), TP53TG3F (100% identical).
Diseases named in the same sentence as TP53TG3 in open-access papers:
TP53TG3 is named in the same sentence as 3 diseases in open-access papers, as found by Europe PMC text mining. Sharing a sentence is not in itself a finding about the gene and the disease. The quoted sentences say what the papers report.
cancer (2 papers, 2024 to 2025). A tumor composed of atypical neoplastic, often pleomorphic cells that invade other tissues. "Gene TP53TG3 was discovered in an analysis of a cancer colon cell line a quarter of a century ago." (PMID 39713347, 2024).
TP53TG3 also shares sentences with these, for which no sentence is quoted: breast carcinoma (1 paper); glioma (1).